ZNF689 (zinc finger protein 689)
Description:
May be involved in transcriptional regulation. Plays a role in transcription regulation.
Synonyms: FLJ90415; TIPUH1
Gene: Protein-coding gene on chromosome 16 (30,602,558 to 30,624,012, reverse strand). Ensembl gene ENSG00000156853.
Subcellular location: Nucleus; Cytoplasm
Subcellular location (Human Protein Atlas): Nucleoli fibrillar center; Nucleoplasm
Pathways (Reactome):
Gene expression (Transcription): Generic Transcription Pathway
Gene Ontology:
Molecular function: DNA-binding transcription factor activity, RNA polymerase II-specific; RNA polymerase II cis-regulatory region sequence-specific DNA binding
Biological process: regulation of transcription by RNA polymerase II; regulation of DNA-templated transcription
Cellular component: nucleus; nuclear lumen
Genetic constraint (gnomAD): Loss-of-function variants: 15 observed, 36.53 expected, observed/expected ratio (o/e) 0.41, 90% interval 0.27 to 0.63. The upper end of that interval is the gene's LOEUF score, 0.63, which puts it in group 2 of 6, group 1 being the genes least tolerant of losing a copy. Missense variants: 573 observed, 699.62 expected, observed/expected ratio (o/e) 0.82, 90% interval 0.76 to 0.88. Synonymous variants: 277 observed, 283.82 expected, observed/expected ratio (o/e) 0.98, 90% interval 0.88 to 1.08.
Homologues: Orthologues: chimpanzee ZNF689 (100% identical), macaque ZNF689 (99% identical), dog ZNF689 (95% identical), pig ZNF689 (94% identical), guinea pig ZNF689 (94% identical), mouse Zfp689 (92% identical), rat Zfp689 (92% identical), rabbit ZNF689 (87% identical), zebrafish znf646 (20% identical), zebrafish si:dkey-89b17.4 (20% identical), Drosophila melanogaster CG1602 (15% identical), Drosophila melanogaster CG18011 (15% identical), and 11 more. Paralogues in human: ZNF785 (41% identical), ZNF764 (35% identical), ZNF747 (27% identical), ZNF420 (27% identical), ZFP92 (26% identical), ZNF48 (25% identical), ZNF84 (25% identical), ZNF91 (25% identical), ZNF574 (25% identical), ZNF688 (25% identical), ZNF160 (24% identical), ZNF184 (24% identical), and 24 more.
Diseases named in the same sentence as ZNF689 in open-access papers:
ZNF689 is named in the same sentence as 6 diseases in open-access papers, as found by Europe PMC text mining. Sharing a sentence is not in itself a finding about the gene and the disease. The quoted sentences say what the papers report.
hepatocellular carcinoma (2 papers, 2020 to 2021). A malignant tumor that arises from hepatocytes. "ZNF689, also known as TIPUH1, promotes the progression of hepatocellular carcinoma by suppressing the apoptotic signaling, and a high ZNF689 level indicates a poor prognosis of hepatocellular carcinoma." (PMID 34638319, 2021).
pancreatic cancer (1 paper, 2021). "Recently, ZNF689 was shown as a direct regulator of pancreatic cancer cell invasion and migration." (PMID 34638319, 2021).
tumor (2 papers, 2020 to 2021). "miRNA-339-5p levels were significantly lower than in classic tumor cells, hypothetically through an effect on its target, zinc-finger protein ZNF689 known to promote tumor progression." (PMID 34207163, 2021).
cancer (1 paper, 2021). A tumor composed of atypical neoplastic, often pleomorphic cells that invade other tissues. "High ZNF689 expression was observed in lower-grade tumors and was negatively correlated with cancer stemness traits." (PMID 34638319, 2021).
ZNF689 also shares sentences with these, for which no sentence is quoted: brain disorder (1 paper); breast carcinoma (1).